BRAF (B-Raf proto-oncogene, serine/threonine kinase)
Diseases named in the same sentence as BRAF in open-access papers (continued):
Sharing a sentence is not in itself a finding about the gene and the disease.
metastatic melanoma (continued). "In summary, we report a case of a patient with complicated hyperbilirubinemia, anemia and hypertransaminasemia related to metastatic melanoma, the patient had BRAF mutant (V600E), because of his aggressive hyperbilirubinemia and performance status it was very hard to choose." (PMID 36865793, 2023). "Neither in the training set nor in the validation set did age, sex, histological subtype, or BRAF mutational status show significant differences between the non-metastatic and metastatic melanoma groups." (PMID 38202181, 2023). "BRAF-wild type samples were majorly encompassed in the clinical global context of absent distant metastases at the time of diagnosis (78.57%, n = 11), with only a small percentage of cases corresponding to metastatic melanomas (21.42%, n = 3)." (PMID 38134090, 2023). "However, only the BRAF inhibitors vemurafenib and dabrafenib and the MEK inhibitors trametinib and cobimetinib have been approved only for BRAF‐V600E/K metastatic melanomas." (PMID 37250144, 2023). "Currently, the guidelines suggest the use of ICIs with anti-PD1, in association or not with anti-CTLA4, in patients with metastatic melanoma, regardless of BRAF status, allowing long-lasting responses and long-time survival in the responders." (PMID 37569757, 2023). "We did not observe statistically significant differences in the RIPK4 protein expression in metastatic melanoma between those with or without BRAF mutations." (PMID 36765875, 2023). "Nodular melanoma histological subtype was found to be an independent risk factor for death in metastatic melanoma patients treated with BRAF- ± MEK-inhibitors but not in those treated with immunotherapy." (PMID 37664072, 2023). "BRAF, NRAS, and NF1 mutational status in metastatic melanoma was not statistically associated with differences in either overall survival or progression-free survival, except for rare patients with BRAF fusions or internal BRAF gene rearrangements." (PMID 37444637, 2023). "In the absence of BRAF mutation, first-line therapy of metastatic melanoma is limited to two options: monotherapy with anti-PD-1 agents (nivolumab or pembrolizumab) or a combination of an anti-PD-1 agent and an anti-CTLA-4 agent (nivolumab and ipilimumab)." (PMID 35911362, 2022). "Several studies have also demonstrated that increasing T cell infiltrates in TME appear in patients with metastatic melanoma treated with BRAF/MEKi, enhancing a favorable anti-tumor microenvironment and decreasing immunosuppressive markers, which implies a higher survival rate." (PMID 36233289, 2022). "The small molecule BRAF inhibitor, encorafenib (LGX818, trade name Braftovi), has been approved by the FDA for the combined treatment of unresectable or metastatic melanoma harboring a BRAFV600E or -V600K mutation (in 2018), and BRAFV600E-mutant metastatic colorectal cancer (in 2020)." (PMID 36559089, 2022). "By determining the BRAF gene status on EVs from plasma samples of metastatic melanoma patients at the beginning and during therapy with BRAF inhibitors, Zocco and collaborators showed that EV-associated DNA can be a better alternative to ctDNA for detection of mutant BRAF in these patients." (PMID 36704194, 2022). "BRAF inhibitor with or without MEK inhibitor for treatment of unresectable or metastatic melanoma and metastatic non-small cell lung cancer with BRAF(V600E) mutation were approved by the U.S. Food and Drug Administration." (PMID 35055392, 2022). "Interestingly, targeted therapies for metastatic melanoma using BRAF inhibitors, such as vemurafenib and dabrafenib that block the active conformation of the BRAF kinase, are associated with a higher risk of cSCC development." (PMID 36721574, 2022). "Furthermore, CCT196969 inhibited viability in two B-Raf Proto-Oncogene (BRAF) inhibitor resistant metastatic melanoma cell lines." (PMID 36084109, 2022). "In 2015, the FDA approved nivolumab in untreated patients with metastatic melanoma without a BRAF mutation." (PMID 36472871, 2022).
metastatic melanoma (continued). "Finally, atezolizumab, in combination with mitogen-activated extracellular kinase (MEK) inhibitor cobimetinib and B-Raf enzyme inhibitor called vemurafenib, has been approved for patients with BRAF V600 mutation-positive unresectable or metastatic melanoma." (PMID 35392976, 2022). "A phase III trial showed that concurrent use of cobimetinib in combination with vemurafenib in patients with BRAF V600-mutant metastatic malignant melanoma results in prolongation of PFS, compared to vemurafenib monotherapy (9.9 months and 6.2 months, respectively)." (PMID 35406444, 2022). "Although BRAFi therapy results in an impressive initial clinical response against BRAF-mutant metastatic melanoma, the durability of this response is limited by the rapid emergence of acquired BRAFi resistance, which often occurs within a few months of treatment initiation." (PMID 35785205, 2022). "Three BRAF inhibitors (vemurafenib, dabrafenib, and encorafenib) and three MEK inhibitors (trametinib, cobimetinib, and binimetinib) are permitted for metastatic melanoma with BRAF V600E or V600K mutations as a single agent or in combination with other agents and exhibit excellent efficacies." (PMID 36254250, 2022). "In the CheckMate-066 study, nivolumab was also shown to associate with significant improvements in overall survival and progression-free survival, as compared with dacarbazine, among previously untreated metastatic melanoma patients, without a BRAF mutation." (PMID 36389735, 2022). "This includes its use as an initial treatment for treatment-naïve patients with metastatic melanoma with or without BRAF V600 mutation where immunotherapy agents have been associated with durable long-term survival in patients with responding disease." (PMID 35626272, 2022). "Since 2015 it has been approved for the treatment of metastatic melanoma in patients without BRAF mutation regardless of programmed death-ligand 1 (PD-L1) expression proving superiority in terms of overall survival compared to chemotherapy with dacarbazine." (PMID 35911362, 2022). "In a clinical validation study, BRAF V600E-mutant circulating tumour DNA (ctDNA) levels at baseline and on treatment appeared to correlate with clinical outcomes in patients receiving targeted therapy for metastatic melanoma." (PMID 35639333, 2022). "A 77-year-old female patient with metastatic melanoma, without BRAF mutation and previous treatment, is the first case presented and treated with nivolumab (240 mg) as a first line at an interval of 14 days." (PMID 34054956, 2021). "Immune checkpoint inhibitors (ICI), including anti-PD1 and anti-CTLA4, as well as targeted therapy with BRAF/MEK inhibitors for BRAF mutant disease have significantly prolonged the survival of patients with metastatic melanoma and are therefore deemed standard of care." (PMID 34063555, 2021). "In metastatic melanoma, we detected BRAF V600E in P1 and P3." (PMID 33799709, 2021). "Akin to the successes of BRAF inhibitors and similar targeted drugs, an expanding type of cancer therapeutics in the form of small molecules aims to couple with existing therapies to improve response rates in metastatic melanoma and other malignancies." (PMID 33810078, 2021). "Treatment options for metastatic melanoma have advanced dramatically in the last ten years, with BRAF inhibitors (e.g., Vemurafenib and Dabrafenib), in mono-therapy or combination-therapy schemes, ameliorating patient survival and improving progression-free disease." (PMID 33922182, 2021). "In addition, in a phase I study, vemurafenib, a BRAF V600E inhibitor approved for metastatic melanoma, was determined to be acceptable for recurrent or refractory BRAF V600E mutant glioma." (PMID 33673070, 2021).
metastatic melanoma (continued). "Researchers have found in clinical studies that the use of BRAF inhibitors in combination with MEK inhibitors in patients with metastatic melanoma can reduce the development of resistance to BRAF inhibitors in patients, thereby enhancing the therapeutic effect." (PMID 34869005, 2021). "Since 2010, vemurafenib has proven its efficacy in BRAF mutant metastatic melanoma." (PMID 34063682, 2021). "To date, the following are approved first-line immunotherapy treatments for unresectable or metastatic melanoma irrespective of BRAF mutation status: nivolumab plus ipilimumab combination, nivolumab monotherapy, and pembrolizumab monotherapy." (PMID 34914610, 2021). "Here, we report the case of a 68-year woman, with a history of four primary cutaneous melanomas (thickest lesion with BRAF mutation removed from the left axilla 2 years before), who was diagnosed with BRAF V600E-mutant metastatic melanoma and treated by ICI targeting the PD-1 receptor." (PMID 33922013, 2021). "In addition to immunotherapy, kinase inhibitors targeting BRAF and MEK are currently standard-of-care options for metastatic melanoma patients with confirmed BRAF V600 mutations." (PMID 33123754, 2021). "Interestingly, nevus eruption has been observed in metastatic melanoma patients treated with single agent selective BRAF inhibitors, consistent with our observation that proliferation arrest in melanocytes requires sustained expression of the oncogene." (PMID 34812139, 2021). "Several phase 3 randomized clinical trials have demonstrated a high ORR and prolonged PFS and OS in front-line and recurrent metastatic melanomas, regardless of their BRAF mutation status." (PMID 34831002, 2021). "Finally, a phase I/II study to investigate the safety and clinical activity of APR-246 in combination with a BRAF inhibitor in patients with mutant-BRAF unresectable metastatic melanoma resistant to anti-BRAF/anti-MEK inhibitors has started (NCT03391050)." (PMID 33540760, 2021). "In a case series of 12 patients with BRAFV600-mutant metastatic melanoma who achieved CR with BRAF/MEK inhibitors and subsequently discontinued treatment, 50% of patients remained relapse-free whereas 50% of patients recurred at a median of 6.6 months after stopping therapy." (PMID 33804800, 2021). "A pooled analysis of the COMBI-d and COMBI-v studies demonstrated the long-term clinical benefit of this combination (dab + tram), reporting a five-year progression-free survival (PFS) rate of 19% and an overall survival (OS) rate of 34% in patients with BRAF V600–mutant metastatic melanoma." (PMID 34070224, 2021). "In this study, we created BRAF-mutant lung metastatic melanoma cells (A375LM5IF4g/Luc) and demonstrated that DETD-35 is more potent at inhibiting A375LM5IF4g/Luc activity in vitro than its parental compound DET, and that GSH depletion and ROS accumulation are important upstream events." (PMID 33810045, 2021). "Vemurafenib and dabrafenib potently inhibit BRAF proteins containing the V600E mutation and are indicated for patients with non-resectable or metastatic melanoma associated with this mutation." (PMID 33653337, 2021). "On the other hand, NRAS mutations slightly outnumbered BRAF mutations in undifferentiated metastatic melanoma with or without known primary." (PMID 33506327, 2021). "It has widely been used in the treatment of BRAF V600E mutant metastatic melanomas." (PMID 34744739, 2021). "In addition, we treated CSK- and PTEN-null OE19 cells with lapatinib and the MAPK inhibitor trametinib (GSK1120212), a drug approved by the FDA in combination with dabrafenib for treatment of patients with BRAF V600E/K-mutant metastatic melanoma." (PMID 34399705, 2021). "BRAF and MEK inhibitors are standard of care for BRAF mutated metastatic melanoma." (PMID 34207200, 2021). "It has been approved by the FDA for the therapy of BRAF V600E mutant metastatic melanoma." (PMID 33216198, 2021).
metastatic melanoma (continued). "Secondly, currently, there is a lack of data on the economic burden for patients with BRAF V600 mutation-positive metastatic melanoma in China." (PMID 34201096, 2021). "However, so far, no studies have addressed the effects of MAPK-directed targeted therapies in patients with BRAF-mutant metastatic melanoma and germline CDKN2A PVs." (PMID 34069952, 2021). "Regardless of BRAF mutational status, the anti-programmed cell death protein 1 (PD-1) monotherapies display significant activity in metastatic melanoma." (PMID 33801689, 2021). "This combination was tested in an open-label phase I study in 21 patients with BRAF V600E-mutated metastatic melanoma, but none of the patients had received BRAF inhibitors before, so none had acquired resistance." (PMID 33003483, 2020). "Thereafter, it received expanded approval in combination with nivolumab for unresectable or metastatic melanoma regardless of BRAF mutation status in 2016, per Phase 3 CheckMate-067 trial data (Category 1)." (PMID 32245016, 2020). "It received its first approval on 4 September 2014, via an accelerated process based on the objective response rate of 24%, from the clinical trial NCT01295827, in metastatic melanoma patients who are refractory to CTLA-4 therapy and BRAF inhibitor if they have BRAF mutation (Category 2A)." (PMID 32245016, 2020). "In addition to evaluation of response to BRAF and MEK inhibitors, HTDS identified notable sensitivities to single agent dinaciclib, vorinostat, ganetespib and doxorubicin across multiple BRAF-mutant metastatic melanoma PDXCs." (PMID 31857724, 2020). "Furthermore, QPRT expression was decreased in metastatic melanoma after the acquisition of resistance to BRAF inhibitors." (PMID 33613454, 2020). "The BRAF and v-raf murine sarcoma viral oncogene homolog B1 inhibitors, vemurafenib and dafrafenib, have been recently approved by the Food and Drug Administration (FDA) for treatment of metastatic melanoma harboring BRAFV600 mutation." (PMID 33028357, 2020). "BRAF/MEK inhibitors have changed metastatic melanoma treatment." (PMID 33150263, 2020). "The purpose of this study was to determine whether the detection of ctDNA, based on the identification of BRAF and NRAS mutations before systemic treatment initiation, was associated with the prognosis of metastatic melanoma." (PMID 32664549, 2020). "Mitogen-activated protein kinase (MAPK) inhibition with the combination of BRAF (Rapidly Accelerated Fibrosarcoma) and MEK (Mitogen-activated protein kinase kinase) inhibitors has become the standard of first-line therapy of metastatic melanoma harbouring BRAF V600 mutations." (PMID 32098410, 2020). "The emergence of BRAF targeted agents such as vemurafenib and dabrafenib allowed tremendous progresses in the field of personalised medicine and demonstrated survival benefits in metastatic melanoma patients as compared to dacarbazine-treated patients." (PMID 32858889, 2020). "To test this hypothesis, we longitudinally evaluated Gal‐1 plasma concentrations at subsequent time points during the course of BRAF/MEK inhibitor therapy (first measurement before drug administration) in 9 metastatic melanoma patients." (PMID 32330348, 2020). "Thus, the combination of dabrafenib with the MEK inhibitor (MEKi) trametinib, has become employed worldwide for the care of patients with BRAF-mutant metastatic melanoma, improving their progression-free and overall survival." (PMID 32604720, 2020). "This study aimed to determine whether the detection of ctDNA, based on the rapid identification of common BRAF and NRAS mutations before systemic treatment initiation, was associated with the prognosis of metastatic melanoma, in an intention-to-treat setting." (PMID 32664549, 2020).
metastatic melanoma (continued). "In this context, a study focusing on tumor samples prior to BRAF inhibitor initiation in metastatic melanoma patients showed improved survival in patients with an immune gene overexpression signature which included both activating and suppressive immune regulators." (PMID 30899440, 2019). "For patients with BRAF-mutant metastatic melanoma, it is unclear whether immunotherapy or kinase inhibitors against BRAF and MEK should be applied in the first-line setting." (PMID 31426419, 2019). "The introduction of monoclonal antibody checkpoint inhibitors, especially the anti-programmed death molecule-1 (anti-PD-1) agents nivolumab and pembrolizumab, and anti-BRAF/MEK agents for patients with BRAF mutations, have revolutionized the treatment of metastatic melanoma." (PMID 31614482, 2019). "Currently, the blockade of certain immune checkpoints such as the cytotoxic T-lymphocyte-associated protein 4 (CTLA-4) and programmed cell death-1 (PD-1) using checkpoint inhibitors is standard of care in patients with metastatic melanoma, especially with BRAF wild-type." (PMID 30828569, 2019). "In a phase III trial, nivolumab dramatically improved PFS (5.1 vs. 2.2 months) and OS at 1 year (72.9 vs. 42.1%) compared with dacarbazine in metastatic melanoma without BRAF mutation." (PMID 31134073, 2019). "This pathway describes the molecular events known to occur during the transition from normal melanocyte to metastatic melanoma, including oncogenic NRAS and BRAF mutations, which activate Raf-MEK-ERK and PI3K-Akt, leading to increased cellular proliferation and cell survival." (PMID 30721246, 2019). "In addition to anti-CTLA-4 antibodies, several anti-PD-1/PD-L1 antibodies were tested in combination with BRAF/MEK inhibitors in metastatic melanoma (NCT01656642, NCT02130466, and NCT02818023)." (PMID 31134073, 2019). "Dabrafenib, like vemurafenib, inhibits BRAF and is used for metastatic melanoma therapy." (PMID 31115969, 2019). "In the light of the results of our study, we retain that the assessment of the BRAF mutation status should be mandatory in SNM cases due to selective inhibition of the MAPK pathway with BRAF and MEK inhibitors for unresectable, advanced metastatic melanomas." (PMID 31581559, 2019). "Furthermore, BRAF and NRAS mutations were confirmed to be mutually exclusive, with a good consistency in mutation distribution between primary and metastatic melanoma lesions." (PMID 29492214, 2018). "We propose that the quisinostat/flavopiridol combination is a promising therapeutic option for both cutaneous and uveal metastatic melanoma patients, independent of their mutational status or (acquired) resistance to BRAF inhibition." (PMID 29464063, 2018). "A 43‐year‐old woman was diagnosed with a BRAF wild‐type metastatic melanoma in 2014." (PMID 30133176, 2018). "BRAF inhibitors vemurafenib and dabrafenib achieved improved overall survival (OS) and/or progression free survival (PFS) over chemotherapy and have been approved for the treatment of BRAF-mutated metastatic melanoma." (PMID 29552321, 2018). "More recently, the clinical and histologic features of cSCCs and other squamoproliferative lesions that complicate treatment for metastatic melanoma with oral small molecule BRAF inhibitors (BRAFi) have raised the possibility of significant viral involvement in their pathogenesis." (PMID 30154763, 2018). "For metastatic melanoma patients without BRAF mutation, therapy with immune checkpoint inhibitors has become first choice." (PMID 30133176, 2018). "In conclusion, results of this trial reveal that the combination of vemurafenib and HD IL-2 in the treatment of BRAF-mutated metastatic malignant melanoma was safe but without added clinical benefit beyond what would be expected with either agent alone." (PMID 30053905, 2018). "It was frequently expressed in metastatic melanoma cell lines independent of their BRAF mutational status and was absent in normal melanocytes." (PMID 28350340, 2017).